CLDN4 (claudin 4)
Diseases named in the same sentence as CLDN4 in open-access papers (continued):
Sharing a sentence is not in itself a finding about the gene and the disease.
tumor (continued). "At the mRNA level, we found that CLDN11 and CLDN4 expression were respectively reduced and increased in CRC tumor samples relative to paracancerous controls as measured via qPCR (n = 10, p < 0.05)." (PMID 35281827, 2022). "Previous studies exploring the effects of CLDN1, CLDN2, CLDN4, CLDN11, CLDN12, CLDN14, and CLDN23 expression on CRC tumor growth have yielded findings consistent with our results in the present study." (PMID 35281827, 2022). "Significant differences in CLDN3, CLDN4, CLDN5, CLDN6, CLDN9, CLDN11, and CLDN12 expression were evident as a function of tumor stage." (PMID 35281827, 2022). "As expected from the combination of the spatial and scRNA sequencing data, we found positive correlations between the expression of INHBA and collective migration marker genes (CLDN4, NECTIN1, and DSG3) at the tumor-stroma interface." (PMID 35986012, 2022). "The xenograft tumor volume of the shCLDN4 + ITD-1 group was significantly reduced, and the tumor development of GBM was inhibited, compared with CLDN4 NC group and control group." (PMID 35418179, 2022). "These candidate markers (CLDN4, EPCAM, CD151, LGALS3BP, HIST2H2BE, and HIST2H2BF) effectively isolated tumor-derived EVs in clinical samples." (PMID 34948417, 2021). "In summary, we detected six DEGs (RIPK4, SCNN1A, SLC4A11, ELF3, CLDN4, and SOBP) which can serve as tumor markers for the diagnosis and prognosis of OC." (PMID 33742531, 2021). "The parameters analyzed were the size of the tumor, the proliferation index (Ki-67 expression), CD24, Claudin 3, and Claudin 4 expression." (PMID 34298771, 2021). "Because of their fast growth rate and ability to establish robust and reproducible subcutaneous tumor xenografts in mice, PSN-1 cells were selected among all claudin-4–expressing PDAC cell lines for further experiments." (PMID 32414951, 2020). "We confirmed that wider tumor necrosis, improved suppression of tumor growth, and improved apoptosis occurred in groups treated with CDDP and the anti-CLDN4 antibody than in other groups." (PMID 31040910, 2019). "Again, the dysregulation of CEP55, CLDN4, CHAF1A, H19 and STEAP4 have been found to significantly correlate with CRC tumor stage, aggressiveness, metastasis and poor prognosis." (PMID 30823889, 2019). "The xenograft tumor samples were then analyzed by IHC for levels of proteins such as HIF-1α, E-cd, Claudin-4, and VIM." (PMID 27806701, 2016). "The YAF-treated tumor samples were analyzed by IHC for levels of HIF-1α/EMT related proteins HIF-1α, E-cd, Claudin-4, and VIM." (PMID 27806701, 2016). "We have found, in tumor cells in culture, that treating with DFYNP or silencing claudin-4 expression can increase tumor cell sensitivity to apoptosis and decrease motility." (PMID 27724921, 2016). "As expected, we found that gene expression patterns are different in PC tumor samples compared to normal, undiseased peritoneum with a number of genes differentially regulated: BAG1, CCNB1, CD44, CLDN4 and 6, MMP2, MKI67, MUC1, MYBL2, and SERPINB3." (PMID 27542596, 2016). "CLDN1 and CLDN2 stained positive in 10–50% of tumor cells, while CLDN4 and CLDN7 stained positive in ≥50% of tumor cells." (PMID 25393310, 2014). "Our data indicate an inverse association between Twist and E-cadherin and Twist and CLDN3 and CLDN4, further attesting to its role in EMT and tumor progression." (PMID 23805314, 2013). "Accordingly, while FKBP5 serves as a measure of HP exposure in pre-tumoral tissue, CLDN4 represents the baseline for tumor structure that HP is not expected to alter on its own." (PMID 41614938, 2026). "WGCNA highlighted module-level structure rather than generic hubs, a tumor-enriched tight-junction/ECM module containing CLDN4, and an HP-enriched steroid/PPAR–lipid module containing FKBP5." (PMID 41614938, 2026). "CLDN4 was also not correlated with tumor metastasis (HR=0.64, p=0.203, in the crude model; HR=0.52, p=0.409, when adjusted for other covariates)." (PMID 40487255, 2025).
tumor (continued). "Using IHC, CLDN4 and CEACAM5 were then evaluated on tumor and healthy tissue sections prepared from paraffin-embedded samples collected from patients who underwent a partial gastrectomy at the Digestive System Surgery Unit, AOU Careggi, Florence (respectively)." (PMID 40868067, 2025). "Although EpCAM, PIGR, OLFM4, and CLDN4 have been previously identified as membrane markers for GC, they did not effectively discriminate between HM and tumor tissue in our patient cohort." (PMID 40868067, 2025). "Meanwhile, genes positively correlated with CLDN4 in expression, such as ANXA2, EZR and ELF3, were also discovered in our study, which were also reported to play a role in tumour progression and might explain the role of CLDN4 in a way." (PMID 38629624, 2024). "It was found that anti-CLDN-4 mAbs significantly inhibited tumor growth in Dutch human CRC and GC mice without significant adverse effects, such as weight loss or liver and kidney damage, in PCa." (PMID 36959784, 2023). "Claudin-4 is highly expressed in pancreaticobiliary ductal PCa (p = 0.015), PanIN, IPMN, MCN, and the major precursor lesions of pancreatic ductal adenocarcinoma, and its expression is correlated with the histological tumor grade of IPMN and MCN." (PMID 36959784, 2023). "In addition, CLDN4 overexpression increased MCF-7 cells’ proliferation, with tumor size in nude mice transplanted with CLDN4-silenced MCF-7 cells being reduced." (PMID 36672179, 2023). "The tumor cells were positive for AE1/AE2, calretinin, WT-1, D2-40, HEG1, EMA, BAP1, and MTAP and negative for carcinoembryonic antigen, MOC-31, Ber-Ep4, ER, PgR, TTF-1, claudin 4, and desmin." (PMID 36896044, 2023). "Meanwhile, downregulation of claudin-4 expression prevented CPE cytotoxicity, and optCPE non-viral in vivo intratumoral injection gene therapy showed targeted anti-tumor effects in different CDX and PDX PCa models, leading to reduced tumor cell viability and induction of tumor necrosis." (PMID 36959784, 2023). "Immunohistochemistry demonstrates negative expression of keratin and claudin-4, and tumor cell nuclei characteristically lack expression of Brahma-related gene-1 (BRG1)." (PMID 36439610, 2022). "CLDN3, CLDN4 and CLDN7 were expressed at an abnormally high level in tumor cells and IM cells." (PMID 35999201, 2022). "However, the matched recurrent tumor samples did exhibit a strong positive correlation between CD44 and both CLDN4 and CLDN7 (Pearson correlation, R= 0.58, p= 0.002 and R= 0.61, p= 0.01, respectively)." (PMID 33828978, 2021). "Basal-like carcinomas, compared to tumor groups of grades 1–3, overexpressed CLDN4, while tumors of grades 1 and 2, displayed decreased, or absent, expression of CLDN4." (PMID 33801373, 2021). "Claudin 4 is expressed in 79% of ER negative tumours and 52% of ER positive tumours and it is particularly high in basal-like tumours." (PMID 31044387, 2020). "Immunofluorescence imaging confirmed claudin-4 overexpression in PSN-1 but not in HT1080 tumor xenografts." (PMID 32414951, 2020). "However, current studies indicate that some members of the claudin family, such as CLDN4 and CLDN1, play an oncogenic role in some types of tumours." (PMID 32093760, 2020). "Genes other than CLDN1, CLDN3, CLDN4, CLDN7, and ZO1 may also be coordinately regulated by DOCK1 and may contribute to tumor growth, but this remains to be investigated." (PMID 31717460, 2019). "Immunohistochemically (IHC) staining revealed that the tumor cells were diffusely positive for cytokeratin (CK) 5/6, p40, desmocollin 3, claudin 4, and MOC31, whereas they were negative for WT1, D2-40, S100 protein, GFAP, CD34, c-kit, NUT, and calponin." (PMID 29625594, 2018).
tumor (continued). "Moreover, the tumor volumes in the lncRNA-KRTAP5-AS1+CLDN4 and lncRNA-TUBB2A+CLDN4 groups were larger (1.58 ± 0.21 cm3 and 1.49 ± 0.21 cm3, respectively) than in the CLDN4 group, which supported the findings of the in vitro experiments." (PMID 28819095, 2017). "The lack of tumor cell response to DFYNP in claudin-4 knockdown cells indicates that DFYNP is specifically targeting claudin-4." (PMID 27724921, 2016). "In the study of Ishikawa xenografts, no significant changes in tumor volume and claudin-4 expression were shown in the paclitaxel group compared with the control group." (PMID 23599806, 2013). "In unkeratinized tumor cells, Cldn-1 was heterogeneously expressed, ZO-1 was weak, whereas Ocln and Cldn-4 were absent." (PMID 23390516, 2013). "No significant changes in tumor volume and claudin-4 expression were shown in the paclitaxel group in this study, however." (PMID 23599806, 2013). "Although we have not observed overt tumor development in Cldn4−/− mice, effects of urinary chemical carcinogens are under investigation." (PMID 23284964, 2012). "CLDN4 was absent or its expression was greatly reduced in tumour cells of 17 out of 21 grade 1 tumours, but it was present in the normal epithelial components within the same blocks (14 IDC NST [no special type], 5 special types, 2 ILC)." (PMID 15743508, 2005). "CLDN4 mRNA expression did not appear to be changed in the invasive tumours in comparison with the surrounding normal tissue." (PMID 15743508, 2005). "According to relative quantification, CLDN4 mRNA expression did not appear to be changed in the invasive tumours in comparison with the surrounding normal tissue." (PMID 15743508, 2005). "Claudin-4 values above 100 were found in 17 samples, with no connection to tumor characteristics." (PMID 39687048, 2024). "It is also expected to inhibit tumor-promoting signals generated by non-TJ CLDN4." (PMID 36982569, 2023). "Meanwhile, the high expression of Claudin-4 might regulate or be regulated by the tumor EMT process, but the present study could not determine cause-to-effect relationships." (PMID 37465316, 2023). "We also found that CLDN4 overexpression increased non-tight junction CLDN4 expression, resulting in increased stemness, likely via activation of integrin β1, suppression of apoptosis, decrease in drug sensitivity, and promotion of tumor growth and metastasis." (PMID 35742959, 2022). "However, positive or negative protein expression of CLDN-4 was reported to be correlated to a larger tumor size of BrCa." (PMID 33407452, 2021). "Hepatic expression of claudin-4 is low, compared with tumor, although claudin-3 expression is not insignificant and may play a role in the differences we have observed." (PMID 32414951, 2020). "Furthermore, uptake of [111In]anti-claudin-4 in HT1080 (no claudin-4 expressing) tumour xenografts was identical to that of [111In]mIgG and therefore did not exceed the level of non-specific uptake resulting from the enhanced permeability and retention effect." (PMID 28842811, 2018). "As expected, the tumor sample population showed higher expression levels of pro-mitotic genes such as CCNB1 and MYBL2, genes that modulate the host immune response, such as SERPINB3, and the tight-junctions proteins claudin-4 and claudin-6, which are often deregulated in cancers." (PMID 27542596, 2016). "Moreover, as with claudin 1, the protein expression of claudin 4 was also found not to be related to nodal status, size of the tumors nor tumor grade." (PMID 23721519, 2013). "From the 45 tumour metastases sections examined, 36% (16 out of 45) had strong, 29% (13 out of 45) had moderate, 20% (9 out of 45) had low and 7% (3 out of 45) had negative staining for claudin-4." (PMID 18648369, 2008).
tumor (continued). "Also, the tumor weights were lower in the miR-596 group (0.54 ± 0.20 g) and miR-3620-3p group (0.51 ± 0.20 g) than in the CLDN4 overexpressing group, but much higher in the lncRNA-KRTAP5-AS1+CLDN4 and lncRNA-TUBB2A+CLDN4 groups (1.04 ± 0.11 g and 1.03 ± 0.13 g, respectively)." (PMID 28819095, 2017). "Finally, neither CLDN4 nor CLDN7 expression was significantly associated with survival of patients with TNBC, which contradicts the previously reported association between CLDN4 expression and BC tumor recurrence." (PMID 25393310, 2014). "The results obtained within this study have revealed a distinct and progressing pattern of claudin-4 expression within the prostate with noncancerous pathological changes as well as in PCa and PCa metastases by RT–PCR and immunohistochemistry of both primary and secondary tumours." (PMID 18648369, 2008). "Reduced expression of CLDN4, but not CLDN3, led to remarkable decreases of cytotoxicity, and the injection of CPE around PC3 xenografts significantly suppressed tumor growth." (PMID 37621953, 2023). "For non-immune cell populations, we identified tumor cells (EPCAM and CLDN4), fibroblasts (COL3A1 and NNMT), and mesothelial cells (LRRN4 and WT1)." (PMID 36788228, 2023). "These tumor cells were negative for SMARCA4, p40, NUT, and claudin-4, leading to establishing a diagnosis of thoracic SMARCA4-deficient undifferentiated malignancy." (PMID 35778998, 2022). "Tumor and non-tumor samples differed significantly in the expression of 10/22 genes: CCNB1, CLDN4, CLDN6, MMP2, MUC1 (all: p < 0.05), BAG1, SERPINB3 (all: p < 0.01), CD44 (standard variant), MKI67, and MYBL2 (all: p < 0.001)." (PMID 27542596, 2016). "Co-treatment with 4D3 increased anti-tumor effects of CDDP, whereas CLDN4 knockdown did not." (PMID 31040910, 2019). "The results showed that CLDN4, lncRNA-TUBB2A, and lncRNA-KRTAP5-AS1 could promote proliferation even after tumor formation compared with their negative controls and that tumor proliferation could be suppressed by miR-596 and miR-3620-3p." (PMID 28819095, 2017). "We also examined motility in human cancer cells lines that lack normal tight junctional organization as determined by loss of ZO-1 expression (data not shown) and are either known to overexpress claudin-4 (T47D, MCF-7, OVCAR3) or known to be particularly aggressive tumor cells (21MT1)." (PMID 23521713, 2013).
cancer (149 papers, 2005 to 2026). A tumor composed of atypical neoplastic, often pleomorphic cells that invade other tissues. "Claudin-4, a tight junction-associated protein that is indicative of epithelial development, is produced by almost all carcinomas." (PMID 40091315, 2025). "We have illustrated CLDN4 as a potential diagnostic marker expressed on cancer cells for recurrent MPE." (PMID 38629624, 2024). "The diversity of non-tight junction functions of CLDIN-4 has attracted much attention, and our studies have shown that CLDN4 overexpression is associated with malignant phenotypes in cancer cells through a variety of mechanisms." (PMID 35742959, 2022). "What’s more, CLDN4 expression was associated with the patient’s age and cancer stage based on TCGA datasets." (PMID 34887379, 2021). "In some types of malignancies, an intrinsic decrease in CLDN4 expression has been associated with the loss of cancer cell adherence, invasion, and metastasis." (PMID 30647838, 2018). "The loss of claudin-1 and claudin-4 characterized more aggressive cancers." (PMID 39458944, 2024). "Notably, the overexpression of certain claudins like claudin-2 and claudin-4 has been linked with increased malignancy and poor patient outcomes, while others such as claudin-1 show variable associations depending on the cancer subtype." (PMID 39364319, 2024). "In BUC, CLDN4 overexpression is associated with cancer progression; however, its epigenetic status remains unclear." (PMID 35742959, 2022). "Claudin (CLDN)-4 expression has been associated with malignancy in various cancers." (PMID 32064037, 2020). "Interestingly, the role of claudin-4 in autophagy and genomic instability, as well as its association with amino acid transporters, strongly suggest a novel and unique clinical significance of claudin-4 in multiple cancer types." (PMID 38867360, 2024). "However, carcinomas with complete loss of Claudin-4 expression have also been described." (PMID 35864317, 2022). "Furthermore, although the function of Cldn3 and Cldn4 is usually associated with tight junctions in normal tissues, they do not appear to have this role in tumors, suggesting a conceivable role of Cldn3 and Cldn4 in cancer progression." (PMID 35006480, 2021). "CLDN-4 integration into tight junctions might be reduced by phosphorylation‒one of the post-translational modifications of CLDNs ‒ and therefore leads to gate function loss in various cancer cell lines." (PMID 33407452, 2021). "Claudin-4 is frequently overexpressed in STAD, and membranous Claudin-4 expression correlates with better prognosis and reduced cancer cell migration and invasion, while also enhancing tight junction barrier function." (PMID 41082105, 2026). "Aberrant CLDN4 expression also weakens tight junction integrity, reducing intercellular adhesion and facilitating cancer cell dissemination." (PMID 40687428, 2025). "Studies suggest that CLDN4 overexpression correlates with poor prognosis and accelerated disease progression in these cancers." (PMID 40487255, 2025). "On the other hand, the diagnostic panel should always be completed with two broad-spectrum carcinoma biomarkers at least, such as claudin-4, Ber-EP4, or MOC-31." (PMID 39941848, 2025). "Based on the survival data of the pure IMPC and IBC-NST cases claudin-4 positive tumors were associated with significantly shorter DMFS, suggesting a role of claudin-4 in cancer progression." (PMID 39687048, 2024). "Rare cancer biomarkers such as Pax8, Pax2, napsinA, carbonic anhydrase IX, claudin-4, Cdx-2, and others have been identified and studied thoroughly to help provide a better diagnosis of rare cancer." (PMID 38256274, 2024). "The expression pattern of CLDN4 on circulating cancer cells denoted its potential for early diagnosis or prediction of recurrent MPE, which also shed lights on the therapeutic strategy of recurrent MPE for advanced NSCLC patients." (PMID 38629624, 2024).